CCDC122 (coiled-coil domain containing 122)
Synonyms: FLJ31846
Tractability: No criterion of Open Targets' tractability assessment is met for any kind of drug.
Gene: Protein-coding gene on chromosome 13 (43,823,909 to 43,880,035, reverse strand). Ensembl gene ENSG00000151773.
Subcellular location (Human Protein Atlas): Vesicles; Nucleoplasm
Genetic constraint (gnomAD): Loss-of-function variants: 25 observed, 22.72 expected, observed/expected ratio (o/e) 1.1, 90% interval 0.8 to 1.53. The upper end of that interval is the gene's LOEUF score, 1.53, which puts it in group 6 of 6, group 1 being the genes least tolerant of losing a copy. Missense variants: 182 observed, 197.87 expected, observed/expected ratio (o/e) 0.92, 90% interval 0.81 to 1.04. Synonymous variants: 55 observed, 61.85 expected, observed/expected ratio (o/e) 0.89, 90% interval 0.71 to 1.11.
Homologues: Orthologues: macaque CCDC122 (96% identical), chimpanzee CCDC122 (83% identical), dog CCDC122 (82% identical), pig CCDC122 (82% identical), guinea pig CCDC122 (78% identical), rabbit CCDC122 (75% identical), mouse Ccdc122 (69% identical), rat Ccdc122 (67% identical), tropical clawed frog ccdc122 (41% identical), Caenorhabditis elegans citk-1 (17% identical), Caenorhabditis elegans citk-2 (16% identical), Drosophila melanogaster SMC3 (12% identical), and 1 more. Paralogues in human: SMC4 (20% identical), SMC1B (19% identical), SMC1A (18% identical), SMC2 (17% identical), CKAP4 (16% identical), SMC3 (14% identical), CCDC157 (13% identical).
Diseases named in the same sentence as CCDC122 in open-access papers:
CCDC122 is named in the same sentence as 1 disease in open-access papers, as found by Europe PMC text mining. Sharing a sentence is not in itself a finding about the gene and the disease. The quoted sentences say what the papers report.
leprosy (3 papers, 2016 to 2025). Leprosy is a chronic infectious disease affecting primarily the skin and peripheral nervous system. "Here, we investigated whether SNPs located in eleven genes: CCDC122/LACC1, IFNG, IL6, IL10, IL23R, LRRK2, NOD2, PACRG/PRKN, TLR1, TNF and TYK2 are associated to leprosy susceptibility in a population in the North of Brazil." (PMID 32433683, 2020). "In a familial sample from Vietnam including 286 MB and 188 PB leprosy patients (WHO-88), signals located in HLA-DR-DQ, RIPK2, CCDC122, LACC1, and NOD2 were validated (p < 0.05), and the effect was stronger in MB patients for HLA-DR-DQ, CCDC122, and LACC1." (PMID 27219008, 2016).